LCN12 (lipocalin 12)
Description:
Binds all-trans retinoic acid and may act as a retinoid carrier protein within the epididymis. May play a role in male fertility (By similarity).
Synonyms: MGC48935
Tractability: Antibody: UniProt places it where antibodies can reach, with high confidence; its Gene Ontology location is reachable by antibodies, with high confidence; UniProt predicts a signal peptide or a membrane-spanning region.
Gene: Protein-coding gene on chromosome 9 (136,949,551 to 136,955,497, forward strand). Ensembl gene ENSG00000184925.
Subcellular location: Secreted
Pathways (Reactome):
Transport of small molecules: Transport of fatty acids
Gene Ontology:
Molecular function: retinoic acid binding; small molecule binding
Cellular component: extracellular region
Genetic constraint (gnomAD): Loss-of-function variants: 14 observed, 20.29 expected, observed/expected ratio (o/e) 0.69, 90% interval 0.46 to 1.08. The upper end of that interval is the gene's LOEUF score, 1.08, which puts it in group 4 of 6, group 1 being the genes least tolerant of losing a copy. Missense variants: 218 observed, 233.04 expected, observed/expected ratio (o/e) 0.94, 90% interval 0.84 to 1.05. Synonymous variants: 116 observed, 106.66 expected, observed/expected ratio (o/e) 1.09, 90% interval 0.94 to 1.27.
Homologues: Orthologues: chimpanzee LCN12 (97% identical), macaque LCN12 (92% identical), mouse Lcn12 (56% identical), dog LCN12 (54% identical). Paralogues in human: LCN2 (34% identical), PTGDS (25% identical), LCN15 (20% identical), LCN1 (18% identical), LCN10 (17% identical), OBP2A (16% identical), LCN6 (15% identical), OBP2B (15% identical), LCN8 (14% identical), LCN9 (14% identical), LCNL1 (12% identical), PAEP (12% identical).
Diseases named in the same sentence as LCN12 in open-access papers:
LCN12 is named in the same sentence as 4 diseases in open-access papers, as found by Europe PMC text mining. Sharing a sentence is not in itself a finding about the gene and the disease. The quoted sentences say what the papers report.
cancer (1 paper, 2021). A tumor composed of atypical neoplastic, often pleomorphic cells that invade other tissues. "There are few studies about LCN12, and its role in cancer has not yet been elucidated." (PMID 33602220, 2021).
infection (1 paper, 2022). The state of being infected such as from the introduction of a foreign agent such as serum, vaccine, antigenic substance or organism. "Given the homology between LCN2, LCN12, and other lipocalin family proteins, one or more of the homologous proteins are likely binding to the polyclonal antibody and are targets that are also upregulated during infection." (PMID 36054235, 2022).
LCN12 also shares sentences with these, for which no sentence is quoted: prostate carcinoma (1 paper); tumor (1).